ADAM17 (ADAM metallopeptidase domain 17)
Diseases named in the same sentence as ADAM17 in open-access papers (continued):
Sharing a sentence is not in itself a finding about the gene and the disease.
nasopharyngeal carcinoma (3 papers, 2021 to 2023). A carcinoma arising from the nasopharyngeal epithelium. "In nasopharyngeal carcinoma cells, miR-145 expression was likewise significantly downregulated, whereas ADAM17 protein expression was upregulated, and ADAM17 had been verified as a target of miR-145." (PMID 36293469, 2022). "Consistent with our data, shRNA silencing of ADAM17 significantly inhibited the invasion and migration of breast and nasopharyngeal cancer cells." (PMID 36293469, 2022).
ovarian tumor (3 papers, 2015 to 2022). "A combination of ADAM17 inhibitor with cisplatin tested in 2D and 3D culture of cells derived from cell lines and primary ovarian tumor- and ascites-derived cells." (PMID 36428724, 2022). "Even in primary ovarian tumor-derived cells, where cisplatin alone was insufficient to induce caspase activation, selective inhibition of ADAM17 enhanced apoptosis four-fold." (PMID 29662625, 2018).
pancreatic adenocarcinoma (3 papers, 2021 to 2023). "Moreover, high expression of ICAM1 and high expression of ADAM10 or ADAM17 was associated with poor clinical outcome in pancreatic adenocarcinoma patients." (PMID 37732732, 2023).
Parkinson disease (3 papers, 2013 to 2025). A progressive degenerative disorder of the central nervous system characterized by loss of dopamine producing neurons in the substantia nigra and the presence of Lewy bodies in the substantia nigra and locus coeruleus. "In neurological disorders, ADAM17 could be involved in the cleavage of neuregulin, affecting synaptic function and contributing to diseases like Alzheimer’s and Parkinson’s." (PMID 40143211, 2025). "sTREM2, cleavage by ADAM10 or ADAM17 is detected in human cerebrospinal fluid (CSF), and its levels are elevated in CSF of patients with various neurological conditions, such as AD, Parkinson’s disease (PD)." (PMID 40636122, 2025). "Some of the players in the outlined route like ADAM17, CX3CL1, DRD1, GRIA1, and LCAM1 have been claimed in animal model studies as therapeutic targets for Parkinson's disease." (PMID 24688734, 2013).
peritonitis (3 papers, 2021 to 2025). Inflammation of the peritoneum (tissue that lines the abdominal wall and covers most of the organs in the abdomen). "Baicalin is associated with the suppression of inflammatory factor expression, likely via modulation of the ADAM17/EGFR axis, and the improvement of the peritonitis injury caused by GPS infection in piglets." (PMID 40867785, 2025). "This is in line with studies investigating ADAM17 null mutant mice in a model of Escherichia coli induced peritonitis." (PMID 37849760, 2023). "Therefore, this study aimed to elucidate the molecular mechanism by which baicalin alleviates GPS-induced peritonitis in piglets, specifically focusing on the role of the ADAM17/EGFR signaling axis." (PMID 40867785, 2025). "In our study, baicalin alleviated the ADAM17/EGFR axis-induced inflammatory injury of peritonitis in PPMCs and piglets infected by GPS, which means that targeting ADAM17 may be the key to alleviating the inflammatory injury of piglet peritonitis." (PMID 40867785, 2025).
pestivirus infection (3 papers, 2022 to 2024). "Here we put forward three lines of evidence that ADAM17 is the missing factor causing the resistance of CRIB-1 cells to pestivirus infection." (PMID 35215974, 2022). "To assess whether additional factors might play a role in the phenotypic resistance of CRIB-1 cells to pestivirus infection, we assessed the effect of ADAM17 expression on the propagation of a fluorophore labelled BVDV clone." (PMID 35215974, 2022). "Therefore, an essential role of ADAM17 in the entry of pestiviruses and in the resistance of CRIB-1 cells to pestivirus infection can be assumed." (PMID 35215974, 2022).
retinoblastoma (3 papers, 2022 to 2024). A malignant tumor that originates in the nuclear layer of the retina. "Taken together, our data suggest that at least ADAM17, being upregulated in RB cells and tissue, might be a promising target for future retinoblastoma therapy strategies as well as a potential diagnostic biomarker." (PMID 36293469, 2022). "These correlation patterns suggest that at least miR-145 is a potential regulator of ADAM10 and ADAM17 in retinoblastoma." (PMID 36293469, 2022). "The study presented focuses on the involvement of ADAM10 and ADAM17 in retinoblastoma (RB), the most common malignant intraocular childhood tumor." (PMID 36293469, 2022). "Interestingly, our group recently demonstrated that ADAM17 is also involved in retinoblastoma tumor progression." (PMID 39695086, 2024). "Thus, the significance of ADAM10 and ADAM17 for tumor growth, tumor cell migration, invasion, and metastasis seems to be cell type dependent, and our data suggest that ADAM17 plays a pivotal role in retinoblastoma development." (PMID 36293469, 2022). "A previous study by our group revealed significantly increased ADAM10 and ADAM17 protein and RNA expression levels in retinoblastoma cell lines, as well as upregulated RNA levels in RB patient tumor samples as compared to the healthy human retina." (PMID 36293469, 2022). "Testing for changes in anchorage-independent growth, soft agarose assays revealed that ADAM10 and ADAM17 depleted Y79, and WERI-Rb1 retinoblastoma cells displayed a significantly reduced colony formation capacity." (PMID 36293469, 2022).
schizophrenia (3 papers, 2021 to 2022). A major psychotic disorder characterized by abnormalities in the perception or expression of reality. "This possibility was supported by a previous study in which schizophrenia patients exhibited significantly higher levels of ADAM17 mRNA in whole blood compared to controls." (PMID 35356722, 2022). "Interestingly, in a study of post-mortem brain samples in individuals with Schizophrenia and bipolar disorder, the levels of TNF-α were negatively correlated with those of Adam17, suggesting anti-inflammatory properties for this gene." (PMID 34573170, 2021).
thoracic aortic aneurysm (3 papers, 2021 to 2025). An aneurysm formed in the wall of the proximal portion of the descending aorta proceeding from the arch of the aorta. "The deficiency of ADAM17 in vascular smooth muscle cells can inhibit the progression of thoracic aortic aneurysms." (PMID 34035876, 2021). "A separate study demonstrated that the deficiency of a disintegrin and metalloproteinase‐17 (ADAM17) in ECs preserves the expression of AJs and TJs, thereby protecting the integrity of the intimal barrier and suppressing the formation of thoracic aortic aneurysm." (PMID 39900554, 2025). "Of interest, pharmacological inhibition of ADAM17, the membrane-bound enzyme and regulator of multiple transmembrane proteins by proteolytic processing, is effective in suppressing thoracic aortic aneurysm formation, as well as its progression in mice." (PMID 35055064, 2022).
vasculitis (3 papers, 2014 to 2021). "ADAM17-rich-EVs reportedly are active and may lead to pathologic conditions, such as vasculitis." (PMID 34208863, 2021). "Elevated levels of ADAM metallopeptidase domain 17 (ADAM17) and α1-trypsin polymers have been reported in PR3-ANCA vasculitis, while the expression of ADAM17 in MPO-ANCA vasculitis has not been tested so far." (PMID 33023023, 2020).
abdominal aortic aneurysm (2 papers, 2020). Enlargement and ballooning of the vessel that supplies arterial blood to the abdomen, pelvis and legs. "With evidence showing that other ADAMs (ADAM10 and ADAM17) play roles in the development of abdominal aortic aneurysm, a recent study demonstrated that ADAM9 expression was up-regulated in a murine abdominal aortic aneurysm model." (PMID 33096780, 2020).
allergic disease (2 papers, 2015 to 2022). An immune response that occurs following re-exposure to an innocuous antigen, and that requires the presence of existing antibodies against that antigen. "Taken together, it is critical to consider both innate B cell levels of ADAM10 and ADAM17 as well as Th context when determining host susceptibility to allergic disease." (PMID 25933166, 2015). "Although further experimental study will be needed to prove our results, the genetic polymorphism of ADAM17 and serum bilirubin level might be used as a potential marker for estimating the risk of allergic diseases and can provide new guidelines for the management of the allergic march." (PMID 35130903, 2022). "Compelling evidence, herein, demonstrates that B-ADAM10, ADAM17, and TNF are differentially regulated in Th1 and Th2-dominated immune responses and directly influence host susceptibility to allergy and IgE production." (PMID 25933166, 2015). "We investigate specifically whether intrinsic differences in B cell ADAM10 levels, independent of Th bias, regulates allergy induction and severity and whether this regulation is associated with modulation of B cell ADAM17 and TNF and associated changes in secondary lymphoid follicular architecture." (PMID 25933166, 2015). "Since B cell levels of ADAM10, ADAM17, and TNF mRNA expression were clearly different in control and allergic patients; and allergy is a Th2-dominated disorder; we sought to confirm our results in classic Th1 and Th2 prone mouse strains." (PMID 25933166, 2015).
alopecia (2 papers, 2022 to 2024). Hair loss usually from the scalp. "ADAM17 (p.D647N) mutation led to hair follicle stem cell (HFSC) exhaustion and caused abnormal hair follicles, ultimately resulting in alopecia." (PMID 38771644, 2024). "The study performed conditional deletion of ADAM17, in RHBDF2 impaired amphiregulin (AREG) mediated sebaceous gland enlargement, wound healing and alopecia suggesting ADAM17 is essential for shedding of EGFR ligand." (PMID 36452073, 2022). "Disruption of HFSCs in Adam17-mutant mice contributes to the woolly hair and alopecia phenotype." (PMID 38771644, 2024).
atopic dermatitis (2 papers, 2021 to 2024). "Similarly, S. aureus is dominant in patients with ADAM17-deficiency related atopic dermatitis, while chronic C. albicans is often associated with impaired Th17 related genes." (PMID 38627868, 2024).
Atrophy (2 papers, 2018 to 2025). Any weakening or degeneration, especially through lack of use. "ADAM17 is weakly expressed in normal kidneys, but its expression is markedly induced in the tubules, capillaries, glomeruli, and mesangium, and it is involved in interstitial fibrosis and tubular atrophy." (PMID 30460232, 2018). "Ligustilide treatment reduced DSS-triggered weight loss, increased DAI scores, reduced spleen enlargement and thymic atrophy, increased colon length, restored colonic pathological structure, increased expressions of ZO-1 and Occludin, and decreased EGR1 downstream target protein ADAM17 expression." (PMID 40904624, 2025).
bacterial sepsis (2 papers, 2017 to 2020). "In particular, ADAM17 was found to promote bacterial sepsis in mice by shedding of TNFα." (PMID 32825187, 2020). "For example, deficiency of ADAM17 in leukocytes clearly reduces inflammatory mediator production and reduces the response to bacterial sepsis, but the absence of this protease does not lead to diminished recruitment of inflammatory cells to inflammatory sites." (PMID 28260841, 2017).
breast invasive carcinoma (2 papers, 2016 to 2022). "Studies have demonstrated that ADAM17 expression levels are increased in invasive breast cancers and correlate with poor prognosis." (PMID 27738494, 2016).
cognitive decline (2 papers, 2023 to 2024). "Interestingly, ADAM17 expression levels are elevated in AD patients compared to healthy individuals, with a significant correlation between elevated plasma ADAM17 activity and cognitive decline in AD patients." (PMID 38963109, 2024). "In conclusion, our study identifies a reduced expression of microvascular ADAM17 as a novel mechanism by which microvascular dysfunction occurs in an AD mouse model and by which it could contribute to the development of cognitive decline and memory deficits." (PMID 36937050, 2023). "Thus, we hypothesized that in the microvasculature, ADAM17 could play an important role in the development of AD neuropathological changes and cognitive decline." (PMID 36937050, 2023).
Crohn disease (2 papers, 2022 to 2024). A gastrointestinal disorder characterized by chronic inflammation involving all layers of the intestinal wall, noncaseating granulomas affecting the intestinal wall and regional lymph nodes, and transmural fibrosis. "Although high levels of TNF are associated with Crohn’s disease, ADAM17 seems to play a protective role in ulcerative colitis, mainly for its ability to trigger EGFR signalling and promote epithelial cell growth and goblet cell differentiation." (PMID 35207132, 2022). "Both ADAM17 and TIMP-3 are constitutively expressed by epithelial cells in the human intestinal barrier, but levels of the inhibitor were found low in patients affected by Crohn’s disease." (PMID 35207132, 2022).
depression (2 papers, 2019 to 2025). "Gallic acid, another plant phenolic, mitigates chronic post-SCI pain and depression by restraining P2X purinoceptor 7 (P2X7)-driven TNF-α/TNF-α–converting enzyme (TACE; ADAM17)/NF-κB/STAT3 signalling." (PMID 41181704, 2025). "In a model of major depressive disorder, TNF-α expression is increased, and an antidepressant treatment decreases the expression of ADAM17 and its targets CXCL2 and IL-6." (PMID 30586315, 2019).
diffuse large B-cell lymphoma (2 papers, 2020 to 2022). "An ADAM17/TACE inhibitory antibody INCB7839 (Aderbasib), in combination with rituximab, is in phase I/II clinical trial as consolidation therapy after autologous hematopoietic cell transplant for patients with diffuse large B cell lymphoma (clinicaltrials.gov identifier: NCT02141451)." (PMID 32273348, 2020).
emphysema (2 papers, 2019 to 2021). "However, animal model data are conflicting with one study suggesting a protective role of ADAM17 in emphysema development, whereas another study suggests ADAM17 activity promotes emphysema development." (PMID 35011566, 2021).
glomerulonephritis (2 papers, 2013 to 2022). A renal disorder characterized by damage in the glomeruli. "In addition, high ADAM17 mRNA expression was significantly associated with interstitial fibrosis and increased serum creatinine levels in patients with glomerulonephritis with or without impaired kidney function." (PMID 35155493, 2022).
glomerulosclerosis (2 papers, 2021 to 2022). A hardening of the kidney glomerulus caused by scarring of the blood vessels. "In CKD, the increase in Ang-II induces disintegrin and metalloproteinase-17 (ADAM17) expression, which activates the epidermal growth factor receptor/mitogen-activated protein kinase (EGFR-MAPK) pathway implicated in fibrosis, glomerulosclerosis, tubular dilation and atrophy." (PMID 36079742, 2022).
Glucose intolerance (2 papers, 2021). Glucose intolerance (GI) can be defined as dysglycemia that comprises both prediabetes and diabetes. "Probably this mild protection against glucose intolerance can be explained by the modulation of Sodium-Glucose Cotransporter-2 (SGLT2) after Adam17 deletion." (PMID 35008648, 2021). "In this line, our study demonstrated that Adam17 deletion on proximal tubular cells prevents increased blood glucose levels and glucose intolerance to a lesser extent." (PMID 34884897, 2021). "Obese animals with tubular Adam17 deletion showed higher glucose intolerance compared to knockout animals fed an SD after 60 min post injection." (PMID 34884897, 2021). "Focusing on glucose homeostasis, obese animals with Adam17 deletion on endothelial cells did not present increased glucose intolerance as compared with controls after 60 min of bolus injection." (PMID 35008648, 2021).
hyperlipidemia (2 papers, 2013 to 2021). "Higher blood glucose levels and hyperlipidemia would lead to the activation of Adam17 that, in turn, stimulates TNF-α shedding and activation." (PMID 34884897, 2021).
hypopharyngeal cancer (2 papers, 2014 to 2023). Carcinoma, predominantly squamous cell, arising from the epithelial cells of the hypopharynx. "In gastric and hypopharyngeal cancer cells, miR-338-3p impedes cell migration and invasion by repressing ADAM17 expression." (PMID 37175410, 2023).
inflammatory skin disease (2 papers, 2018 to 2020). Inflammatory skin disorders covers a broad category that includes many conditions ranging in severity, from mild itching to grave medical health complications These disorders are common in people of all ages and races. "Subsequently, another patient with ADAM17/TACE mutations resulting in inflammatory skin disease, recurrent infections, and fatal sepsis was identified." (PMID 33324405, 2020). "Our data revealed that p63 has an impact on ADAM17 and its associated substrates, demonstrating a role of p63 in inflammatory skin diseases." (PMID 29523849, 2018). "In 2011, a syndrome including inflammatory skin disease and recurrent infections was linked to autosomal recessive mutations in ADAM17/TACE in two siblings." (PMID 33324405, 2020).
interstitial lung disease (2 papers, 2025). A diverse group of lung diseases that affect the lung parenchyma. "Initially, an assessment was made of ADAM17 protein levels in patients diagnosed with connective tissue diseases–interstitial lung diseases (CTD‐ILD), using ELISA assays." (PMID 40077919, 2025).
intestinal cancer (2 papers, 2019 to 2025). "This moreover illustrates the complexity of CRC and the central role of the metalloprotease ADAM17 in intestinal cancer development." (PMID 31060243, 2019). "In a recent study, it was shown that the absence of ADAM17 in a genetic intestinal cancer background (APCMin/+) resulted in less intestinal tumors, which were also of low-grade dysplasia." (PMID 31060243, 2019).
iron overload (2 papers, 2018 to 2019). "Since ADAM17 expression is associated with ectodomain shedding of TNF-α and sCD1637, our results suggest that the increase in sCD163 and TNF-α is associated with iron-overload and activation of ADAM17 in SAH patients." (PMID 29980709, 2018). "Of these only 3 genes (CD163, ADAM17, and TMED7) were significantly linked to systemic iron-overload based on multivariate projection model analyses." (PMID 29980709, 2018). "Livers of patients with iron-overload, showed significantly increased levels of CD163 and ADAM17, correlating with the increase in sCD163 and TNF-α levels." (PMID 29980709, 2018). "These events could be inhibited with iron chelation or with ADAM17-blockade, postulating a therapeutic strategy for SAH patients with iron overload." (PMID 29980709, 2018).
Kawasaki disease (2 papers, 2022 to 2024). A rare inflammatory disease characterized by an acute febrile, systemic, self-limiting, medium-vessel vasculitis primarily affecting children. "Furthermore, Kawasaki disease and secondary coronary artery lesions are found to be associated with ADAM17 genetic variants through TGF-β/Smad3 signaling pathway." (PMID 36313337, 2022).
keloid (2 papers, 2007 to 2021). An irregularly shaped, elevated mark on the skin caused by deposits of excessive amounts of collagen during wound healing. "While monocyte-derived inflammatory dendritic cells (DC) were the main infiltrating immune cell population, the striking upregulation of ADAM10, ADAM17 and Neprilysine in lesional fibroblasts may point to a prominent role of these proteases in the pathogenesis of keloids." (PMID 34502327, 2021). "The elevated protease levels in keloid fibroblasts coincided with close proximity to CD45+ immune cells, as ADAM10, ADAM17 and CD10 reveal a high expression predominantly found in lesional fibroblasts." (PMID 34502327, 2021).
metastatic colorectal cancer (2 papers, 2021 to 2022). "Herein, we show that the level of exosome-derived ADAM17 is elevated in the serum of patients with metastatic colorectal cancer as well as in metastatic colorectal cancer cells." (PMID 34650435, 2021).